SOX2 (SRY-box transcription factor 2)
Diseases named in the same sentence as SOX2 in open-access papers (continued):
Sharing a sentence is not in itself a finding about the gene and the disease.
prostate carcinoma (continued). "Loss of Sox2 expression in the castration-resistant CWR-R1 prostate cancer cell line inhibited cell growth." (PMID 23326489, 2013). "Furthermore, the expression levels of SOX2 have been shown to be inversely associated with chemotherapy resistance and poor prognostic outcomes in prostate cancer." (PMID 39976818, 2025). "SOX2 plays a pivotal role in the molecular mechanisms associated with prostate cancer." (PMID 39976818, 2025). "In addition, SOX2 employed the activities of canonical reprogramming, glycolytic, and oxidative phosphorylation reactions in prostate cancer cells different from those associated with canonical SOX2 function in ESCs." (PMID 35629138, 2022). "In prostate cancer, elevated SOX2 expression is associated with poor prognosis and relapse." (PMID 34809669, 2021). "Finally, the orphan nuclear receptor NR2F1 has been linked to tumor cell dormancy in prostate cancer through induction of pluripotency genes, such as SOX2 and NANOG." (PMID 32220301, 2020). "This study demonstrates a key role of SOX2/OCT4-associated prostate cancer stem cells in tumor development and therapeutic resistance, and identifies the SORE6 reporter system as a useful tool for characterizing CSCs functions in a native tumor microenvironment." (PMID 31500347, 2019). "In prostate cancer, SOX2 expression is associated with low expression of both miR-145 and miR-34b." (PMID 28388544, 2017). "Furthermore, SOX2 has been implicated in the evasion of apoptotic signals in prostate cancer, gastric cancer and NSCLC." (PMID 27225481, 2016). "SOX2 has been implicated in paclitaxel resistance in prostate cancer cell lines." (PMID 27225481, 2016). "Moreover, Sox3 was identified as a target of retroviral insertions causing T-cell lymphomas in mice and the Sox2 locus is frequently amplified in prostate cancer." (PMID 21483788, 2011). "Moreover, SOX2 is known to increase glycolysis in prostate cancer cells, although the association between glycolysis and SOX2-mediated VM formation remains unclear." (PMID 38044399, 2023). "This inquiry seeks to deepen our understanding of SOX2's role in prostate cancer and to identify more effective therapeutic strategies." (PMID 39976818, 2025). "The research indicated that SOX2 expression levels were notably elevated in prostate cancer tissues when compared to those with Inflammation of the prostate gland and benign prostatic hyperplasia." (PMID 39976818, 2025). "Ongoing clinical trials are currently evaluating targeted SOX2 therapy for prostate cancer, and additional clinical data will be required in the future to validate its efficacy and safety." (PMID 39976818, 2025). "Research has shown that in prostate cancer, SOX2 can suppress E-cadherin expression by activating the WNT/β-catenin signaling pathway, which facilitates EMT." (PMID 39976818, 2025). "ADT induces the expression of CIgG in prostate cancer, with SOX2 playing a crucial role in its up-regulation." (PMID 39976818, 2025). "Targeting SOX2 offers significant potential for developing effective therapies not only for prostate cancer, but also for other tumors, thereby facilitating innovative approaches to cancer treatment." (PMID 39976818, 2025). "Furthermore, SOX2 is intricately linked to the metastatic capabilities of prostate cancer cells; it may affect their migration and invasion behaviors while enhancing the adaptability of tumor cells to external conditions, thus promoting metastasis and invasion." (PMID 39976818, 2025).
prostate carcinoma (continued). "SOX2 is found not only in most castration-resistant metastatic prostate lesions but also within castration-sensitive prostate cancer cells." (PMID 39976818, 2025). "This transformation in prostate cancer relies on the increased expression of stem cell reprogramming factors like SOX2 and EZH2." (PMID 40507907, 2025). "This review highlights the role of SOX proteins in prostate cancer, focusing on the molecular mechanisms by which SOX2 drives cancer progression, elucidating the mechanisms controlling its activity, and emphasizing its potential as a therapeutic target." (PMID 40821114, 2025). "A substantial body of research demonstrates a significant correlation between SOX2 and prostate cancer." (PMID 39976818, 2025). "Recent technological advancements have led to significant progress in targeted gene therapy, and our comprehension of SOX2's role in prostate cancer has similarly deepened." (PMID 39976818, 2025). "This article reviews the structural domains, normal physiological functions, and role in prostate cancer progression of SOX2, providing potential targets for prostate cancer treatment." (PMID 39976818, 2025). "Ethan P Metz and colleagues have elucidated that the role of SOX2 in various tumor cell types, including prostate cancer, adenocarcinoma of the Pancreatic Duct, and medulloblastoma cells, is concentration-dependent." (PMID 39976818, 2025). "To reduce the proliferation and survival of prostate cancer cells, we can design specific small molecule inhibitors that target SOX2 activity, effectively suppressing its expression or function." (PMID 39976818, 2025). "Recent studies have highlighted the critical role of the SOX family transcription factors, especially SOX2, in prostate cancer pathogenesis." (PMID 40821114, 2025). "SOX2 enhances the progression, invasion, and metastasis of prostate cancer through various mechanisms, while also playing a role in the development of drug resistance." (PMID 39976818, 2025). "Prostate cancer: SOX2 expression was upregulated in 72% of prostate cancer cases (p < 0.001), particularly in high Gleason score tumors and advanced disease stages." (PMID 40674376, 2025). "Based on threshold fold-change values (>2.0), elevated expression of SOX2 was observed in 76% of colorectal, 60% of breast, and 72% of prostate cancer cases." (PMID 40674376, 2025). "Recent studies have demonstrated that in prostate cancer, both SOX2 and components of the Hedgehog signaling pathway (HH) are subject to amplification." (PMID 39976818, 2025). "The elevated expression of SOX2 in prostate cancer cells promotes the EMT, with TGF-β1 further amplifying this phenomenon." (PMID 39976818, 2025). "SOX2 not only acts as a crucial biomarker for lymph node metastasis in prostate cancer but also serves as an important therapeutic target for this condition." (PMID 39976818, 2025). "Another study consistently showed that the JAK–STAT1/IFIT5/SOX2 axis facilitates the acquisition of stemness in prostate cancer cells." (PMID 39372390, 2024). "SOX2 also promotes tumorigenesis and malignant transformation in prostate cancer by regulating metabolic reprogramming and enhancing glycolytic capacity." (PMID 38879516, 2024).
prostate carcinoma (continued). "Several researchers have observed a connection between SOX2 expression and various clinical aggressions, as well as the development of cancer resistance, including lung, breast, and prostate cancers." (PMID 39062149, 2024). "The relationship between SOX2 expression and CSCs is well-established in a variety of cancer types, and SOX2 positive prostate cancer stem cells play an essential role in tumour development and therapeutic resistance." (PMID 36968194, 2023). "Further studies found that SOX2 expression was higher in tumor cells with relatively low sensitivity to radiotherapy, for example, in prostate cancer, SOX2 expression was upregulated in tumor cells that survived fractionated radiotherapy." (PMID 37213675, 2023). "It was reported that the SRY-related HMG-box gene 2 (SOX2) is responsible for the epigenetic reprogramming of prostate stem cells (PSCs) toward prostate cancer stem cells (PCSCs) in PCa." (PMID 38008751, 2023). "For example, the introduction of SOX2 in prostate cancer induces stem-like characteristics but uses different metabolic pathways and interacts with different target gene products." (PMID 35629138, 2022). "Cistrome analysis reveals that genomic sites bound by SOX2 in prostate cancer cells vary from the canonical ones, leading to oncogenic pathway activation and metabolic reprogramming." (PMID 35682963, 2022). "It was shown that overexpression of SOX2 is accompanied by the resistance of prostate cancer cells to the chemotherapeutic agent paclitaxel." (PMID 35309116, 2022). "Altogether, the results signify that STAT6 and SOX2 and their genomic alterations can be explored in therapeutic interventions of prostate cancer for precision oncology, utilizing early diagnosis and target-propelled therapy." (PMID 35719950, 2022). "The SOX2 and SOX9 genes are overexpressed in advanced prostate cancer and SOX9 is linked to decreased response to early treatment and to biochemical recurrence." (PMID 35682963, 2022). "A recent study from our group has demonstrated high expression of ALDH1high, Oct4 and Sox2 in clinical prostate cancer specimens undergoing ADT, compared to grade-matched controls." (PMID 35800367, 2022). "A study conducted on prostate cancer tissue specimens indicated Oct4, Sox2 and Nanog genes as prostate CSC markers." (PMID 35800367, 2022). "The KM survival shows that the patients with prostate cancer held STAT6 and SOX2 alterations, linked to the decreased survival of the patients." (PMID 35719950, 2022). "We found overexpressed STAT6 and SOX2 and proposed them as candidate biomarkers and potential targets in prostate cancer." (PMID 35719950, 2022). "Hypoxia-inducible miR-1181 is a known tumour suppressor in cancers such as pancreatic, ovarian and prostate cancer and is shown to target SOX2, STAT3 and HOXA10 to inhibit proliferation, migration and invasion and to promote EMT43–47." (PMID 35190587, 2022). "Weighted gene co-expression network analysis (WGCNA) suggests a set of five dysregulated hub genes (MAF, STAT6, SOX2, FOXO1, and WNT3A) that played crucial roles in biological pathways associated with prostate cancer progression." (PMID 35719950, 2022). "We found that a high-fat diet induces lineage plasticity in prostate cancer epithelial cells by increasing SOX2 expression in both coculture and xenograft models." (PMID 35884514, 2022). "A recent study has shown that, in DU145 prostate cancer cells, ClC‐3 also acts as a signalling molecule that directly interacts with the stem cell factor SOX2, and then, the two co‐regulate the cell cycle." (PMID 34952996, 2022). "The point mutations and their types in SOX2 and STAT6 in prostate cancer patients shows significant mutation frequency." (PMID 35719950, 2022).
prostate carcinoma (continued). "Collectively, these results suggest that not only in melanoma, but also in prostate cancer SOX2 expression is controlled via Usp9x." (PMID 33613844, 2021). "Among other cancers, prostate cancer is known to be driven by TFs such as ERG, and SOX2 has been implicated as well." (PMID 33613844, 2021). "SOX2 and hedgehog signaling together promote prostate cancer cell proliferation and migration and prevent apoptosis." (PMID 34809669, 2021). "For example, it has been shown that AR can directly bind the enhancer element within the SOX2 promoter in prostate cancer cells, resulting in the inhibition of SOX2 transcription." (PMID 33420371, 2021). "SOX2 plays a critical role in EGFR-mediated self-renewal of human prostate cancer stem–like cells derived from DU145 cells." (PMID 34809669, 2021). "In fact, it has been suggested that SRRM4 mediates increased SOX2 expression, driving prostate cancer cells to a pluripotent phenotype and favoring tumor growth." (PMID 33621242, 2021). "The role of SOX2 in prostate cancer is well-established and it has been shown that SOX2 is one of the key drivers of lineage plasticity promoting drug resistance associated with aggressive forms of prostate cancer." (PMID 33572108, 2021). "We also observed reciprocal regulation between SLUG and TWIST1, which leads to induction of SOX2 and stemness in prostate cancer cells, possibly contributing to the accelerated aggressiveness of the malignancy." (PMID 34809669, 2021). "Castration-resistant BMI1+SOX2+ prostate cancer cells play an important role in prostate cancer recurrence." (PMID 33499351, 2021). "The rationale behind this study was a previous report demonstrating that CD44 can raise Sox2 expression in prostate cancer cells." (PMID 33228022, 2020). "Collectively, we have shown the direct role of SOX2 in the transcriptional regulation of SPINK1 in prostate cancer." (PMID 31959826, 2020). "Aberrant SOX2 expression is noted, particularly in castration-resistant prostate cancer cells where ligand activation of AR promotes a decrease in SOX2 expression as a result of direct binding of the AR to the SOX2 cis-enhancer region." (PMID 33339129, 2020). "In line with reports that SOX2 is essential for NED in prostate cancer, we found that SOX2 regulon was upregulated across almost all NE cells from patient #2 and #5." (PMID 33328604, 2020). "Significantly, elevating SOX2 in vivo in pancreatic ductal adenocarcinoma, medulloblastoma, and prostate cancer cells induced a reversible state of tumor growth arrest." (PMID 32998722, 2020). "In prostate cancer, SOX2 has been shown to promote resistance to antiandrogen therapy by initiating lineage plasticity." (PMID 33339129, 2020). "Xenotransplantation assays provided evidence that SOX2 promoted tumorigenesis and, particularly, increased the antiapoptotic properties of human prostate cancer cells." (PMID 31366128, 2019). "Here, we show that a fluorescent reporter called SORE6 can identify SOX2/OCT4-overexpressing prostate cancer cells." (PMID 31500347, 2019). "In supporting the activity of the SORE6 reporter as a detector of SOX2 and OCT4 expression, SORE6+ prostate cancer cells expressed higher levels of SOX2 and OCT4 than SORE6− cells." (PMID 31500347, 2019).
prostate carcinoma (continued). "Reports in the literature have documented the association between LIN28, NANOG, POU5F1, and SOX2 and prostate cancer aggressiveness individually." (PMID 31146720, 2019). "We found that the prostate cancer stem cell subpopulation overexpress stem cells markers such as Nanog, c-Myc and Sox2 which play important roles in cancer stemness signaling." (PMID 30728896, 2019). "Our studies show that the SORE6 reporter is a robust system for identifying SOX2/OCT4-overexpressing prostate cancer cells with CSC characteristics." (PMID 31500347, 2019). "It is also important that SOX2 overexpression in prostate cancer cell lines resulted in androgen-independent growth." (PMID 31366128, 2019). "So, we suggest a role played by RAGE and SOX2 in the progression of prostate cancer that they can be used as predictive tools or therapeutic targets in prostate cancer." (PMID 30806068, 2019). "Recent identification of pluripotency markers (Nanog, c-Myc, Sox2) in prostate cancer stem cells and characterization of their unique molecular properties have opened up possibilities about how they can be targeted for more effective therapies." (PMID 30728896, 2019). "Similar observations have been made also for SOX2 whose expression in prostate cancer correlated with histologic and Gleason score." (PMID 31366128, 2019). "SOX2, an important transcription factor, has been shown to be over-expressed in most human cancer types, including prostate cancer." (PMID 30806068, 2019). "For example, SOX2 is known to be responsible for resistance to anti-androgen based therapy in prostate cancer." (PMID 30382189, 2019). "In conclusion, RAGE and SOX2 were up-regulated in prostate cancer; mainly in cancers with a worse prognosis which have higher Gleason Grade, higher Gleason Score and higher Gleason Grade Group." (PMID 30806068, 2019). "It is also well known that SOX2 promotes metastasis of breast and prostate cancer cells via activation of the Wnt/β-catenin pathway." (PMID 30453543, 2018). "In particular, Russo and colleagues showed that SOX2 was expressed in NEPC murine models whereas others found its expression restricted to NEPC areas of advanced human prostate cancer." (PMID 29888169, 2018). "For example, in the cases of colorectal cancer and prostate cancer, SOX2-expressing tumors have been shown to correlate with increased distant and lymphatic metastases." (PMID 28388544, 2017). "EGF signaling is critical for self-renewal of human prostate cancer stem cells by regulation of Sox2 expression." (PMID 28345658, 2017). "In prostate cancer, the inhibition of LncRNA H19 can repress the expression of classic stem cells related factors SOX2 and Oct4." (PMID 28245841, 2017). "Overexpression of SOX2 is detected in recurrent prostate cancer, head and neck squamous cell carcinoma, glioblastoma, small-cell lung cancer, and cancers of the breast, liver, pancreas, and stomach." (PMID 29259714, 2017). "SOX2 has been shown to be located in the cytoplasm or both nucleus and the cytoplasm in several cancer tissues, such as lung and prostate cancer." (PMID 27791206, 2016). "The PI3K/Akt signaling pathway has been shown to be activated in prostate cancer cells overexpressing SOX2." (PMID 27225481, 2016). "A decrease in the expression of the pluripotency transcription factors Oct4 and Sox2 was also observed in human prostate cancer cells following knockdown of H19." (PMID 26415227, 2015).